MLEC (malectin)
Description:
Carbohydrate-binding protein with a strong ligand preference for Glc2-N-glycan. May play a role in the early steps of protein N-glycosylation (By similarity).
Synonyms: KIAA0152
Tractability: Small molecule: a structure with a bound ligand is known. Antibody: its Gene Ontology location is reachable by antibodies, with high confidence; UniProt predicts a signal peptide or a membrane-spanning region. PROTAC: ubiquitination databases record sites on it; its protein half-life has been measured.
Gene: Protein-coding gene on chromosome 12 (120,687,125 to 120,704,282, forward strand). Ensembl gene ENSG00000110917.
Subcellular location: Endoplasmic reticulum membrane
Pathways (Reactome):
Immune System: Neutrophil degranulation
Metabolism of proteins: N-glycan trimming in the ER and Calnexin/Calreticulin cycle
Gene Ontology:
Molecular function: enzyme binding; protein binding; protein-folding chaperone binding; carbohydrate binding
Cellular component: membrane; endoplasmic reticulum; endoplasmic reticulum membrane; plasma membrane; specific granule membrane
Genetic constraint (gnomAD): Loss-of-function variants: 7 observed, 26.31 expected, observed/expected ratio (o/e) 0.27, 90% interval 0.15 to 0.5. The upper end of that interval is the gene's LOEUF score, 0.5, which puts it in group 2 of 6, group 1 being the genes least tolerant of losing a copy. Missense variants: 237 observed, 349.01 expected, observed/expected ratio (o/e) 0.68, 90% interval 0.61 to 0.76. Synonymous variants: 142 observed, 142.61 expected, observed/expected ratio (o/e) 1, 90% interval 0.87 to 1.14.
Homologues: Orthologues: chimpanzee MLEC (100% identical), macaque MLEC (99% identical), dog MLEC (97% identical), pig MLEC (96% identical), guinea pig MLEC (95% identical), rabbit MLEC (95% identical), rat Mlec (95% identical), mouse Mlec (94% identical), tropical clawed frog mlec (81% identical), zebrafish mlec (72% identical), Drosophila melanogaster CG9257 (45% identical), Caenorhabditis elegans F44E2.10 (33% identical).
Diseases named in the same sentence as MLEC in open-access papers:
MLEC is named in the same sentence as 4 diseases in open-access papers, as found by Europe PMC text mining. Sharing a sentence is not in itself a finding about the gene and the disease. The quoted sentences say what the papers report.
papillary thyroid carcinoma (1 paper, 2020). "Overexpression of MLEC was considered as one of the new markers in papillary thyroid carcinoma." (PMID 32153636, 2020).
cancer (2 papers, 2021). A tumor composed of atypical neoplastic, often pleomorphic cells that invade other tissues. "Unfortunately, the role of SLITRK4 and MLEC in cancer has not been illustrated yet." (PMID 33442423, 2021).
infection (2 papers, 2020 to 2022). The state of being infected such as from the introduction of a foreign agent such as serum, vaccine, antigenic substance or organism. "Though many genes were up-regulated in INGR15002 after infection, only one gene (Os03g0281466) encoding malectin serine threonine kinase was up-regulated in the qBL3 fine mapped region." (PMID 32166467, 2020). "In cluster 1, several malectin genes, the expression of which was significantly suppressed in the course of the infection, were found." (PMID 35050051, 2022). "We hypothesize that malectin transmembrane domain may receive the external cues in response to blast infection and trigger the signal transduction using the kinase domain." (PMID 32166467, 2020).
tumor (1 paper, 2018). "Additionally, our study is the first to show evidence of the gene Malectin (MLEC) being a tumor suppressor." (PMID 29871649, 2018).